TAF13 (TATA-box binding protein associated factor 13)
Description:
The TFIID basal transcription factor complex plays a major role in the initiation of RNA polymerase II (Pol II)-dependent transcription. TFIID recognizes and binds promoters via its subunit TBP, a TATA-box-binding protein, and promotes assembly of the pre-initiation complex (PIC). The TFIID complex consists of TBP and TBP-associated factors (TAFs), including TAF1, TAF2, TAF3, TAF4, TAF5, TAF6, TAF7, TAF8, TAF9, TAF10, TAF11, TAF12 and TAF13. TAF13, together with TAF11 and TBP, play key roles during promoter binding by the TFIID and TFIIA transcription factor complexes.
Synonyms: TAF(II)18; TAFII-18; TAFII18; TAF2K; MRT60
Tractability: Small molecule: a structure with a bound ligand is known. PROTAC: ubiquitination databases record sites on it.
Gene: Protein-coding gene on chromosome 1 (109,062,496 to 109,076,012, reverse strand). Ensembl gene ENSG00000197780.
Subcellular location: Nucleus
Subcellular location (Human Protein Atlas): Nucleoplasm; Nucleoli
Pathways (Reactome):
Gene expression (Transcription): RNA Polymerase II Pre-transcription Events; RNA Polymerase II Promoter Escape; RNA Polymerase II Transcription Initiation; RNA Polymerase II Transcription Initiation And Promoter Clearance; RNA Polymerase II Transcription Pre-Initiation And Promoter Opening; RNA polymerase II transcribes snRNA genes
Disease: HIV Transcription Initiation; RNA Polymerase II HIV Promoter Escape; Transcription of the HIV genome
Gene Ontology:
Molecular function: protein binding; TBP-class protein binding; RNA polymerase II general transcription initiation factor activity; DNA binding; protein heterodimerization activity
Biological process: mRNA transcription by RNA polymerase II; positive regulation of transcription initiation by RNA polymerase II; RNA polymerase II preinitiation complex assembly; DNA-templated transcription initiation; transcription by RNA polymerase II; transcription initiation at RNA polymerase II promoter
Cellular component: nucleolus; nucleoplasm; nucleus; transcription factor TFIID complex
Genetic constraint (gnomAD): Loss-of-function variants: 4 observed, 8.88 expected, observed/expected ratio (o/e) 0.45, 90% interval 0.22 to 1.03. That is too few expected variants to judge how well the gene tolerates losing a copy. Missense variants: 86 observed, 115.76 expected, observed/expected ratio (o/e) 0.74, 90% interval 0.62 to 0.89. Synonymous variants: 42 observed, 37.17 expected, observed/expected ratio (o/e) 1.13, 90% interval 0.88 to 1.46.
Homologues: Orthologues: chimpanzee TAF13 (100% identical), macaque TAF13 (100% identical), mouse Taf13 (100% identical), rabbit TAF13 (100% identical), rat Taf13 (100% identical), guinea pig TAF13 (99% identical), pig TAF13 (94% identical), tropical clawed frog taf13 (94% identical), zebrafish taf13 (88% identical), Drosophila melanogaster Taf13 (67% identical), Caenorhabditis elegans taf-13 (41% identical). Paralogues in human: SUPT3H (24% identical).
Diseases named in the same sentence as TAF13 in open-access papers:
TAF13 is named in the same sentence as 4 diseases in open-access papers, as found by Europe PMC text mining. Sharing a sentence is not in itself a finding about the gene and the disease. The quoted sentences say what the papers report.
microcephaly (2 papers, 2019 to 2022). A congenital or acquired developmental disorder in which the circumference of the head is smaller than normal for the person's age and sex. "Recent exome sequencing studies have produced compelling evidence that pathogenic variants in TAF1, TAF2, TAF8 and TAF13 are linked to intellectual disability and microcephaly." (PMID 30948355, 2019). "First, variants in TAF1, TAF2, TAF8 and TAF13 have all been linked to intellectual disability and microcephaly." (PMID 30948355, 2019). "TAF13 (TATA-box-binding-protein-associated factor 13, MIM 600774), associated with ID combined with microcephaly, was excluded due to its autosomal recessive pattern." (PMID 36277487, 2022).
tumor (1 paper, 2022). "We identified 14 prognostic DNA repair-related genes and provided evidence that DCTN4 and TAF13 may serve as a tumor promotor in TC." (PMID 35035484, 2022).
TAF13 also shares sentences with these, for which no sentence is quoted: Intellectual disability (1 paper); invasive breast carcinoma (1).